AMACR (alpha-methylacyl-CoA racemase)
Description:
Catalyzes the interconversion of (R)- and (S)-stereoisomers of alpha-methyl-branched-chain fatty acyl-CoA esters. Acts only on coenzyme A thioesters, not on free fatty acids, and accepts as substrates a wide range of alpha-methylacyl-CoAs, including pristanoyl-CoA, trihydroxycoprostanoyl-CoA (an intermediate in bile acid synthesis), and arylpropionic acids like the anti-inflammatory drug ibuprofen (2- (4-isobutylphenyl)propionic acid) but neither 3-methyl-branched nor linear-chain acyl-CoAs.
Synonyms: RACE; P504S; AMACRD; CBAS4; RM
Tractability: Antibody: its Gene Ontology location is reachable by antibodies, with high confidence. PROTAC: ubiquitination databases record sites on it; its protein half-life has been measured.
Gene: Protein-coding gene on chromosome 5 (33,986,165 to 34,008,104, reverse strand). Ensembl gene ENSG00000242110.
Subcellular location: Peroxisome; Mitochondrion
Subcellular location (Human Protein Atlas): Peroxisomes; Vesicles; Cytosol; Plasma membrane
Pathways (Reactome):
Metabolism: Beta-oxidation of pristanoyl-CoA; Synthesis of bile acids and bile salts via 24-hydroxycholesterol; Synthesis of bile acids and bile salts via 7alpha-hydroxycholesterol
Protein localization: Peroxisomal protein import
Gene Ontology:
Molecular function: alpha-methylacyl-CoA racemase activity; catalytic activity
Biological process: bile acid metabolic process; bile acid biosynthetic process; fatty acid beta-oxidation using acyl-CoA oxidase; fatty acid metabolic process
Cellular component: cytoplasm; mitochondrion; peroxisome; cytosol; peroxisomal matrix
Genetic constraint (gnomAD): Loss-of-function variants: 17 observed, 20.58 expected, observed/expected ratio (o/e) 0.83, 90% interval 0.56 to 1.24. The upper end of that interval is the gene's LOEUF score, 1.24, which puts it in group 5 of 6, group 1 being the genes least tolerant of losing a copy. Missense variants: 493 observed, 484.19 expected, observed/expected ratio (o/e) 1.02, 90% interval 0.94 to 1.1. Synonymous variants: 209 observed, 183.49 expected, observed/expected ratio (o/e) 1.14, 90% interval 1.02 to 1.28.
Gene-disease validity (ClinGen):
ClinGen rates the evidence that AMACR causes each of these diseases.
alpha-methylacyl-CoA racemase deficiency (autosomal recessive): Definitive.
Homologues: Orthologues: chimpanzee AMACR (97% identical), guinea pig AMACR (79% identical), rat Amacr (78% identical), mouse Amacr (77% identical), tropical clawed frog amacr (63% identical), zebrafish amacr (63% identical), Drosophila melanogaster Amacr (51% identical), Caenorhabditis elegans C24A3.4 (38% identical), Caenorhabditis elegans ZK892.4 (37% identical). Paralogues in human: SUGCT (27% identical).
Diseases named in the same sentence as AMACR in open-access papers:
AMACR is named in the same sentence as 140 diseases in open-access papers, as found by Europe PMC text mining. Sharing a sentence is not in itself a finding about the gene and the disease. The quoted sentences say what the papers report.
prostate carcinoma (138 papers, 2005 to 2026). A carcinoma that arises from epithelial cells of the prostate gland. "The loss of canonical prostate cancer markers (AMACR, AR, NKX3.1, and PSA) between biopsy and cell line establishment reflects the cellular evolution commonly observed in treatment-resistant disease." (PMID 41038711, 2025). "AMACR (alpha-methylacyl-CoA racemase), a key enzyme involved in fatty-acid metabolism, serves as a well-established diagnostic biomarker that is markedly overexpressed in prostate-cancer epithelium compared with benign glands." (PMID 41292954, 2025). "In summary, while the association of AMACR gene and protein expression with cancer risk and prognosis is well-established for prostate cancer, there is limited evidence that this association is modified by PA." (PMID 31436750, 2020). "A causal relationship between this SDK1:AMACR fusion and prostate cancer progression remains to be clarified." (PMID 32982686, 2020). "A meta-analysis combining five case-control studies found that D175G and M9V polymorphisms of the AMACR gene were associated with prostate cancer risk." (PMID 31436750, 2020). "The protein expression profile included ERG, AMACR (prostate cancer associated), and Prostein (prostate epithelium specific) of cells captured from the post-DRE urine specimens." (PMID 31013716, 2019). "In prostate cancer, miR-186 often exhibits diminished expression, and its down-regulation correlates with the elevated expression of several prostate cancer-associated genes, such as alpha-methylacyl-CoA racemase and prostate-specific membrane antigen gene." (PMID 25742499, 2015). "Meanwhile, the low expression of AMACR was independently associated with the development of metastasis and lethal in prostate cancer through regulating lipid metabolism and nuclear receptor activity." (PMID 24839399, 2014). "Further, we detected AMACR expression in tumor with immunohistochemistry and analyzed its association with genotype regarding prostate cancer risk." (PMID 24383053, 2013). "An AMACR spliced variant was reported capable of creating a novel transcript that is expressed with other forms of AMACR in prostate cancer." (PMID 24383053, 2013). "Further, we analyzed the risk of prostate cancer in relation with AMACR polymorphism in cases of AMACR expression." (PMID 24383053, 2013). "Sequence variants of AMACR have been previously investigated to find their association with prostate cancer risk." (PMID 24383053, 2013). "We concluded that the genetic variations of AMACR were associated with the risk of sporadic prostate cancer treated with radical prostatectomy in ethnically homogenous population of Korean men." (PMID 24383053, 2013). "Despite the new findings that the sequence variants of AMACR are related to the risk of sporadic prostate cancer in the ethnically homogenous population of Korean men, caution should be taken when interpreting our findings due to some limitations." (PMID 24383053, 2013). "Genetic variations of AMACR are associated with the risk of sporadic prostate cancer that underwent radical prostatectomy in Koreans." (PMID 24383053, 2013). "The chromosomal region of AMACR has been validated as a susceptible locus for prostate cancer, including hereditary prostate cancer." (PMID 24383053, 2013). "In the case group expressing AMACR protein, individuals with the AG or GG genotype of rs2278008 showed a decreased prostate cancer risk compared to those with the AA genotype (adjusted OR 0.47; 95% CI, 0.26–0.87, P = 0.017)." (PMID 24383053, 2013). "This is the first report ever for the analysis of the combinatorial effect of AMACR SNPs on the prostate cancer susceptibility in haplotype." (PMID 24383053, 2013). "Some studies identified chromosome 5p13, the site of the gene encoding (R)-alpha-methyl-CoA racemase (AMACR), as the location of a prostate cancer susceptibility gene." (PMID 24383053, 2013).
prostate carcinoma (continued). "In patients expression AMACR, AG or GG genotype was also significant genotype in terms of prostate cancer risk (adjusted OR, 0.47; 95% CI, 0.26–0.87, P value = 0.017)." (PMID 24383053, 2013). "So, we conclude that in conjunction with morphology and clinical scenario, a combination of HMWCK and AMACR is of great value in combating the morphologically suspicious cases and thus significantly increasing the diagnostic accuracy in prostate cancer." (PMID 21176184, 2010). "A combination of HMWCK and AMACR is of great value in combating the morphologically suspicious cases and significantly increasing the diagnostic accuracy in prostate cancer." (PMID 21176184, 2010). "The CD26+ cancer cells also had elevated expression of prostate cancer-associated genes AMACR (α-methylacyl-CoA racemase), HPN (hepsin) and PCA3 (prostate cancer antigen 3)." (PMID 20021671, 2009). "To characterise GOLPH2 as a new diagnostic tissue marker of prostate cancer, we conducted a careful comparison with the well-established AMACR immunohistochemistry." (PMID 18781151, 2008). "In addition, AMACR has high sensitivity and specificity in prostate cancer, and overexpression of AMACR in prostate cells is associated with poor patient prognosis." (PMID 37660062, 2023). "In addition, as a result of sequencing the promoter portion of AMACR in prostate cancer, 17 sequence variants were identified." (PMID 32760737, 2020). "Polymorphic variants in the PTEN (rs2735343),PI3K (rs2699887), AKT1 (rs2494750),AR (rs17302090), and AMACR (rs3195676)genes were evaluated as possible molecular markers of susceptibility, prognosis,and progression of prostate cancer (PCa), in a case-control study." (PMID 32484847, 2020). "Furthermore, polymorphisms in the AMACR gene have been linked with elevated risks of prostate cancer in several independent studies." (PMID 25132681, 2014). "Recent evidence suggests that the prostate cancer (PCa)-specific up-regulation of certain genes such as AMACR, EZH2, PSGR, PSMA and TRPM8 could be associated with an aberrant expression of non-coding microRNAs (miRNA)." (PMID 24517338, 2014). "A-Methyl Coenzyme A racemase (AMACR): This gene product is involved in oxidation of fatty acids found in dairy products and beef, the consumption of which has been associated with increased risk of prostate cancer." (PMID 24282788, 2013). "Based on this result, the genetic polymorphism of AMACR might influence the development of prostate cancer for patients expressing AMACR." (PMID 24383053, 2013). "The use of Korean men, who are reported as an ethnically homogenous population, may deliver useful conclusion for the association of AMACR polymorphisms with prostate cancer risk, by reducing the possible influences related to genetic heterogeneity." (PMID 24383053, 2013). "Furthermore, in subjects expressing AMACR, the association of rs2278008 with prostate cancer risk also showed statistical significance." (PMID 24383053, 2013). "Over-expression of AMACR may increase the risk of prostate cancer, because its expression is increased in premalignant lesions (prostatic intraepithelial neoplasia)." (PMID 25586028, 2012). "Indeed, the AMACR gene was first found to be abnormally active in prostate cancers, and its abnormal expression has become a diagnostic marker for the cancer." (PMID 19148275, 2009). "Our investigation of the relationship between genotype frequencies, haplotype pair, and the expression of AMACR protein in tumors with clinical features demonstrates that sequence variants of AMACR may play an important role in the development of prostate cancer." (PMID 24383053, 2013). "IHC assessed key prostate cancer markers (AR, AMACR, KLK3, PTEN, NKX3-1, VIM), while WES compared somatic alterations in PGCA, adjacent adenocarcinoma, and stromal tissue." (PMID 40873563, 2025).
prostate carcinoma (continued). "In another study where authors mined TCGA data, isolating 319 prostate-cancer DEGs enriched in xenobiotic-metabolism pathways, network analysis pinpointed AMACR, FOLH1, and NPY as core hubs." (PMID 40806607, 2025). "Protein levels and activity of human AMACR (P504S) are increased in prostate cancer and other cancers, and the enzyme is a recognized drug target." (PMID 40447188, 2025). "In particular, AMACR is significantly upregulated in prostate cancer and has been proven to be an effective biomarker for early diagnosis in prostate cancer patients." (PMID 41421797, 2025). "Knockdown of human AMACR in prostate cancer cell lines reduces proliferation and is synergistic with androgen deprivation." (PMID 40447188, 2025). "AMACR is known to be overexpressed in prostate cancer and is thought to metabolically support tumor growth through β-oxidation of certain fatty acids, as well as damage DNA through peroxide production." (PMID 38173042, 2024). "Our observations suggest a potential mechanistic link between DNA hypomethylation and AMACR gene expression in prostate cancer." (PMID 38566104, 2024). "The expression of AMACR can be variable among prostate cancer histotypes; however, it maintains high sensitivity." (PMID 39858412, 2024). "AMACR has been widely used since it was first reported as a novel molecular marker for prostate carcinoma." (PMID 39336516, 2024). "The top three overexpressed genes whose differential expression was associated with prostate cancer are PCA3, SPINK1, and AMACR, which encode prostate cancer antigen 3, serine protease inhibitor Kazal-type 1, alpha-methylacyl-CoA racemase." (PMID 38173042, 2024). "Similar to prostate cancer cells and derived PDOs, early PCCs and PDOs derived from them expressed cancer markers AMACR, TMPRSS2-ERG, and EZH2." (PMID 36769153, 2023). "In contrast, late PCCs lost expression of epithelial markers, although PCCs prepared from PCaT continued to express androgen receptor (AR1) and prostate cancer markers AMACR and EZH2." (PMID 36769153, 2023). "AMACR expression in prostate cancer was correlated with PTEN expression in prostate cancer (p = 0.039)." (PMID 37185705, 2023). "Immunohistochemical staining of prostate carcinoma marker AMACR and basal cell markers p63 and 34βE12 are widely-used tools in detecting neoplastic prostate glands lacking basal cell layer." (PMID 37415848, 2023). "In this case, both the prostate and cervical lymph node biopsies showed positive staining results for PSA and AMACR, leading to the diagnosis of cervical lymph node metastasis of prostate cancer." (PMID 37660062, 2023). "Similar to the early antigens identified for breast and colon cancer, silencing gene expression of either HPN or AMACR significantly inhibits prostate cancer cell growth." (PMID 35948756, 2022). "To confirm that ACRJ-PC28 is a prostate cancer cell line, we first examined at the protein level, the presence of prostate specific biomarkers, AR, AMACR, NKX3.1, and PSA." (PMID 36643868, 2022). "Overexpression of AMACR occurs in the majority of prostate cancers as well as 90% (125/140) of cases of high-grade PIN21,34." (PMID 35948756, 2022). "Fourth, AMACR is only expressed in prostate cancer NE cells, and this gene was expressed in ACRJ-PC28 at RNA and protein levels." (PMID 36643868, 2022). "Several peroxisomal proteins such as α-methylacyl-CoA racemase (AMACR) are elevated in various tumour types, including prostate cancer (PCa) and patients with PCa often display increased plasma phytanic acid levels." (PMID 35169201, 2022). "The expression of common prostate cancer biomarkers, including AR, AMACR, PSA, PSMA, ERG, and neuroendocrine markers (synaptophysin, chromogranin A and CD56) were continually assessed across PDX generations." (PMID 34413304, 2021). "We also examined markers for prostate cancer such as AMACR, EPCAM and C-MYC as well as molecular markers CDH1 and PTEN." (PMID 34911933, 2021).
prostate carcinoma (continued). "Additional AMACR inhibitors designed on the basis of a structure–activity relationship analysis also efficiently suppressed prostate cancer progression." (PMID 32674458, 2020). "According to the reported results, the expression of AR and IGF-1 in prostate cancer decreased as the expression of AMACR decreased." (PMID 32760737, 2020). "The depletion of AMACR in prostate cancer cells with high AMACR expression impaired cell proliferation by arresting the cell cycle in G2/M." (PMID 32674458, 2020). "Currently, AMACR gene expression is used in prostate cancer diagnosis in combination with other biomarkers such as 34E12, CK5/6 or p63 or with prostate cancer antigen 3, as AMACR is most consistently upregulated in prostate cancer tissue." (PMID 31436750, 2020). "We have not proved the importance of PA2G4 and Ki67 for CaP detection as they weakly correlated with some prostate cancer-related markers (e.g., AMACR), but also with leukocyte-specific CD45 and house-keeping genes (TBP and RHOA)." (PMID 32630458, 2020). "Univariate and multivariate regression analysis of genotypes and alleleof PTEN, AKT1, PI3K, AR, and AMACR genesin controls and patients with prostate cancer." (PMID 32484847, 2020). "AMACR mRNA detected in cancer tissues increased by 682 times compared to normal tissue in patients with prostate cancer, and increased by 11.5 times for AR mRNA." (PMID 32760737, 2020). "According to the results reported so far, target drugs that inhibit the expression of AMACR in prostate cancer are typically ibuprofenoyl-CoA derivatives, and 2-(phenylthio)propanoyl-CoA derivatives." (PMID 32760737, 2020). "AMACR has emerged as a prostate cancer marker, and its expression is high in other cancers such as colon cancer, liver cancer, and renal cancer, and it is a potential target of anti-cancer drugs." (PMID 33154941, 2020). "Univariate regression analysis between genotypes of PTEN, AKT,PI3K, AR, and AMACR genes withclinicopathological features in prostate cancer patients." (PMID 32484847, 2020). "AMACR activity inhibitors identified by small molecule screening were reported to impair the proliferation and survival of prostate cancer cells." (PMID 32674458, 2020). "Using post-DRE urine, prostate cancer cells have been detected using multiple color fluorescent staining for AMACR, Nkx3.1, Nucleolin, and DAPI." (PMID 31013716, 2019). "Expression of AMACR (which is upregulated in prostate cancer with high-grade prostatic intraepithelial neoplasia) in PrCEC was not significantly different than the PC3 cells whereas PrEC cells showed significantly decreased expression." (PMID 31355132, 2019). "The peroxisomal α-methylacyl-CoA racemase (AMACR) expression was found to be highly elevated in tissue from prostate carcinoma if compared to benign prostate tissue." (PMID 30219925, 2018). "Here, we used a molecular-genetic imaging strategy to exploit the transcriptional specificity of the AMACR promoter for the in vivo detection of prostate cancer using the reporter gene luciferase." (PMID 30613352, 2018). "Alpha-methylacyl-CoA racemase (AMACR) is highly overexpressed in prostate cancer (PCa) and its transcriptional regulators include various transcription factors and CTNNB1/β-catenin." (PMID 29471827, 2018). "Since this initial publication, numerous studies have confirmed elevated levels of AMACR as a reliable prostate cancer tumor marker." (PMID 30219925, 2018). "In the early 2000s, two research groups independently verified AMACR as a prostate cancer (PCa) biomarker based on its specific overexpression in malignant tissue compared to benign prostate tissue by immunohistochemistry (IHC)." (PMID 30613352, 2018). "The levels of serum and urine levels of AMACR and Netrin 1 were 10.2 ±9.8 ng/mL; 6.8 ±2.5 ng/mL; 159.1 ±44.1 pg/mL and 20.1 ±5.3 pg/mL respectively in prostate cancer group." (PMID 30104809, 2018).